FAP (fibroblast activation protein alpha)
Diseases named in the same sentence as FAP in open-access papers (continued):
Sharing a sentence is not in itself a finding about the gene and the disease.
pulmonary fibrosis (continued). "Our data highlight that the overwhelming majority of myofibroblasts in bleomycin-induced pulmonary fibrosis in mice are FAPα+." (PMID 39768155, 2024). "It was previously demonstrated that FAPα was expressed in lesions of lung fibrosis, particularly in fibrotic interstitium and in fibroblast foci of IPF patients." (PMID 39364020, 2024). "In human IPF, immunohistochemical studies on lung biopsies showed that FAP is strongly expressed in areas of lung fibrosis, namely in fibroblast foci and interstitium, and is positively correlated with the severity of fibrosis." (PMID 39188902, 2024). "FAPα levels were also assessed in BALFs from controls and patients with idiopathic pulmonary fibrosis (IPF)." (PMID 37880678, 2023). "Altogether, BALF FAPα concentration appears then useful to monitor therapeutic response in preclinical models of lung fibrosis and probably more sensible than the measurement of OH-proline and the Ashcroft modified scale." (PMID 37880678, 2023). "It was shown that the presence of FAP-expressing fibroblasts actually was protective in a mouse model of lung fibrosis." (PMID 38004406, 2023). "The measurement of FAPα in BALF appears to be a promising marker of the fibrotic activity in preclinical models of lung fibrosis and in IPF patients." (PMID 37880678, 2023). "FAP expression has been found on the surface of fibroblasts, e.g., in lung fibrosis, which has prompted the evaluation of available FAP-targeting radioligands also in fibrotic disease." (PMID 38004406, 2023). "Recently, fibroblast activation protein (FAP), an overexpressed transmembrane protein of activated fibroblast in pulmonary fibrosis, has been considered as the new target for diagnosing and treating pulmonary fibrosis." (PMID 35957641, 2022). "So FAP has become the target of pulmonary fibrosis diagnosis and therapy, which interests many researchers." (PMID 35957641, 2022). "The treatment with the FAP-targeted PI3K inhibitor slows lung fibrosis, suppresses the production of hydroxyproline (major building block of collagen), reduces collagen deposition, and extends life in mouse models of pulmonary fibrosis." (PMID 35453505, 2022). "For instance, FAP+ cell depletion by T cells expressing FAP chimeric antigen receptors or global FAP knockout showed increased level of pulmonary fibrosis in bleomycin-induced lung fibrosis, but had only minimal effects on the Ad-TGFβ induced model." (PMID 34335301, 2021). "FAP expression has been detected in tumor stroma, and several different fibrotic diseases, such as idiopathic pulmonary fibrosis and cirrhosis." (PMID 24402778, 2014). "The study was not intended to assess long-term therapeutic efficacy or systemic safety, but rather to examine the feasibility of FAP-directed fibroblast targeting by primary human CAR-NK cells in pulmonary fibrosis and to provide a basis for further preclinical investigation." (PMID 42123706, 2026). "FAP is upregulated in activated fibroblasts during the active phase of fibrosis and its expression decreases as fibrosis progresses to a chronic stage whilst structural fibrosis persists in the bleomycin-induced pulmonary fibrosis mouse model." (PMID 41471268, 2025). "Given its direct involvement in pericyte transition to myofibroblast, PDGFRβ-targeted imaging may provide complementary insights to FAP imaging in pulmonary fibrosis." (PMID 40664934, 2025). "Similarly, FAP is overexpressed by fibroblasts in inflammatory conditions and fibrosis, such as liver cirrhosis and idiopathic pulmonary fibrosis." (PMID 38695960, 2024). "In addition, the presence of a soluble form of FAPα, enabling the measurement of it in biological fluids, makes it a potential biomarker for the evaluation and follow-up of lung fibrosis." (PMID 39364020, 2024). "In addition to its high expression in tumor tissues, FAP expression is up-regulated in a variety of fibrotic diseases, including hepatic fibrosis, pulmonary fibrosis, and myocardial fibrosis." (PMID 39086477, 2024).
pulmonary fibrosis (continued). "Therefore, we are exploring the possibility of FAP-CAR T cells in the treatment of pulmonary fibrosis and its mechanism of action, and corresponding progress has been made, which will be presented in subsequent articles." (PMID 39086477, 2024). "Activated fibroblasts play a pivotal role in the pathogenesis of pulmonary fibrosis by contributing to fibrosis and inflammation following expression of FAP, which is selectively expressed on activated stromal fibroblasts during tissue remodeling and is associated with PF." (PMID 38872212, 2024). "Similarly, FAP overexpression has been detected in various fibroblast-mediated inflammatory conditions such as liver cirrhosis and idiopathic pulmonary fibrosis." (PMID 38695960, 2024). "Several miRNAs, such as miR-30a and miR-204, have been found to be negatively correlated with FAP expression and were not only involved in the induction of FAP expression by TGF-β1 in interstitial pulmonary fibrosis, but were also verified to target and inhibit FAP directly in oncological studies." (PMID 37006278, 2023). "We also identify that determination of FAPα concentration in BALF could be an outstanding marker of the fibrotic activity in preclinical lung fibrosis models and in IPF patients." (PMID 37880678, 2023). "Moreover, FAPα levels were strongly correlated with lung fibrosis as measured by the modified Aschroft histological analysis, hydroxyproline and the percentage of weight loss." (PMID 37880678, 2023). "However, this interpretation is at odds with the previous preclinical literature indicating the presence of FAP as a protective mechanism in lung fibrosis, presumably through its fibrolytic activity." (PMID 38004406, 2023). "Therefore, multicenter studies should be initiated to validate the use of BALF FAPα as a biomarker of lung fibrosis and prognosis of IPF." (PMID 37880678, 2023). "Whilst expressed at low levels in healthy tissue, upregulation of FAP on fibroblasts can be found in several solid organ malignancies, including non-small cell lung cancer, and chronic inflammatory conditions such as pulmonary fibrosis and rheumatoid arthritis." (PMID 35359378, 2022). "Furthermore, there is increasing evidence of the role of FAP in additional fibroproliferative conditions such as idiopathic pulmonary fibrosis, hepatic fibrosis, rheumatoid arthritis and myocardial infarction." (PMID 35359378, 2022). "FAP can be induced by fibrosis foci during pulmonary fibrosis in ongoing tissue remodeling." (PMID 36531015, 2022). "In this work, mesoporous polydopamine (MPDA), which is facile prepared and easily modified, is developed as a carrier to load antifibrosis drug pirfenidone (PFD) and linking FAP inhibitor (FAPI) to realize lesion-targeted drug delivery for pulmonary fibrosis therapy." (PMID 35957641, 2022). "FAP is also found to be highly expressed in the collagen-accumulated loci of several fibrotic diseases including keloid, liver fibrosis, myocardial infarction, lung fibrosis, Crohn’s disease, and arthritis." (PMID 34335301, 2021). "Moreover, a soluble form of FAPα could be identified in biological liquids, rendering this protein a promising candidate as a biomarker for progressive lung fibrosis." (PMID 39364020, 2024). "Thus, our studies have shown that the intratracheal administration of extracellular vesicles secreted by MSCs to mice in a model of bleomycin-induced lung fibrosis can reduce the number of FAPα-expressing cells in the lung tissue, which correlates with a decrease in the severity of fibrosis." (PMID 38136590, 2023). "To test this hypothesis, we studied FAPα expression in a mouse model of lung fibrosis." (PMID 37880678, 2023). "In this study, we established a primary human FAP-CAR-NK-cell platform and conducted a proof-of-concept evaluation in pulmonary fibrosis-related models, including in vitro systems, a human pulmonary fibrosis-like organoid model, and an acute in vivo observation model." (PMID 42123706, 2026).
pulmonary fibrosis (continued). "In conclusion, oleuropein exerts its beneficial effects by targeting FAP-α and inhibiting TGF-β1-related signaling pathways, improving the pathological characteristics of pulmonary fibrosis in mouse models, and demonstrating promising application prospects for the treatment of IPF." (PMID 41008517, 2025). "In our study, FAP expression was increased in the PHMG-p-treated group as observed on the Western blot, consistent with previous reports demonstrating increased FAP expression in pulmonary fibrosis." (PMID 41515504, 2025). "After nuclear export, cytoplasmic lnc668 promoted the translation and stability of PICALM mRNA, leading to increased levels of differentiation-related and fibrotic proteins, such as FAP, α-SMA, COL1A, COL3A, and VIM, thus contributing to the progression of pulmonary fibrosis." (PMID 40221424, 2025). "FAP PET also has the potential to predict and monitor response to anti-fibrotic agents, such as nintedanib and pirfenidone that are used clinically to slow down pulmonary fibrosis." (PMID 39572227, 2025). "Preliminary studies in small cohorts of patients have shown increased FAP PET signal in a wide range of settings including cardiac injury, interstitial lung disease and pulmonary fibrosis, IgG4-related disease, cirrhosis, renal injury, inflammatory bowel disease and rheumatoid arthritis." (PMID 39572227, 2025). "Some studies could also be conducted to confirm the expression of FAPα by alveolar epithelial cells and verify whether it can be a novel marker of cells undergoing EMT in lung fibrosis." (PMID 39364020, 2024). "In this study, using the well-established model of murine bleomycin-induced pulmonary fibrosis, we have shown that FAPα+ cells, but not M2 macrophages, are observed in lung tissue on day 3 and 7 after injury." (PMID 39768155, 2024). "Moreover, FAP expression is also increased in several nonmalignant diseases where active tissue remodeling is involved, including hepatic fibrosis, idiopathic pulmonary fibrosis, atherosclerosis, rheumatoid arthritis, and myocardial infarction." (PMID 33996747, 2021).
lymph node metastasis (30 papers, 2015 to 2026). "The association between FAP-α expression and metastasis, including distant metastasis, lymph node metastasis, blood vessel invasion, vascular invasion, and neural invasion, was evaluated." (PMID 38751814, 2024). "FAP was also linked to lymph node metastases and histological subtypes, as indicated by our findings." (PMID 37752545, 2023). "High FAP expression in all patients significantly increased the risk of lymph node metastasis (OR: 3.80, P = 0.004)." (PMID 25775399, 2015). "Further stratification analysis indicated that the patients with FAP overexpression in group B had a greater risk of lymph node metastasis than those patients in group A (OR: 4.95, P < 0.001 vs OR: 3.53, P = 0.035, respectively)." (PMID 25775399, 2015). "FAP expression in CRC stroma is positively associated with lymph node metastasis." (PMID 37316886, 2023). "Moreover, FAP-positive pancreatic stellate cells are associated with more lymph node metastasis and poorer survival." (PMID 37316886, 2023). "Moreover, concomitant FAP/nuclear BCAT expression in lymph node metastases was independently associated with worse DFS of AdC patients." (PMID 32428869, 2020). "Third, fortunately, the analyses indicate that worse outcomes correlated with a higher risk of lymph node metastasis in patients with FAP overexpression, demonstrating that node metastasis might be a primary approach for tumor migration in these patients." (PMID 25775399, 2015). "Specifically, the expression level of FAP in patients with stage N1 (presence of lymph node metastasis) was significantly higher than that in patients with stage N0 (absence of lymph node metastasis) and in normal tissues (p < 0.01)." (PMID 40430845, 2025). "According to recent reports, FAP overexpression in CRC contributes to adverse clinical outcomes such as increased lymph node metastasis, tumor recurrence, and angiogenesis, as well as decreased overall survival." (PMID 37316886, 2023). "The study showed that lymph node metastasis in the high FAP expression group was higher than in low FAP expression groups (60.43% vs. 33.4%, respectively)." (PMID 37316886, 2023). "Univariate analyses revealed that α-SMA, FAP, and lymph node metastasis were significant factors, but histopathologic subtypes were not an independent factor." (PMID 37007101, 2023). "Compared to the low FAP expression group, its overexpression significantly correlated with higher lymph node metastasis." (PMID 37316886, 2023). "Multivariate Cox regression analysis showed FAP expression in GCAFs and lymph node metastasis to be independent predictive markers for the survival prognosis of patients." (PMID 30038550, 2018). "The outcomes included the relations between FAP expression and histological differentiation, tumor invasion, lymph node metastasis, distant metastasis and overall survival (OS)." (PMID 25775399, 2015). "Three patients presented with distant (lymph node metastases n = 3 (affection of paraaortal and mediastinal lymph node metastases), peritoneal metastases n = 2, bone metastases n = 1), FAP positive metastases at the preoperative FAPI scan (all [68Ga]Ga-FAPI- 46 scans)." (PMID 40272498, 2025). "However, the detection rate of lymph node metastases was inferior, presumably due to low FAP expression in small metastases." (PMID 33057927, 2021). "In OSCC, FAP expression could be correlated with tumor size, lymph-node metastasis and shorter overall survival." (PMID 34050405, 2021). "The FAP expression of lymph node metastases also appears to correlate with the size of the lesion." (PMID 33057927, 2021). "It has been demonstrated very recently that FAP-targeting fluorescent immunoliposomes can be used for intraoperative imaging and may improve the accurate and complete resection of tumors and lymph node metastases." (PMID 28033421, 2016).
lymph node metastasis (continued). "In those patients with FAP expression only in stroma tumors, although tumor invasion and lymph node metastasis correlated with FAP overexpression, the overall survival of these patients was not statistically significant compared with that in patients with lower FAP expression." (PMID 25775399, 2015). "The detection capability of [68Ga]Ga–FAP‐2286 PET for primary lesions, distant metastases, and lymph node metastases is superior to that of 18F‐FDG." (PMID 40656546, 2025). "In a direct comparison of 18F-FDG and 68Ga-FAPI, a preoperative PET/CT staging study of lymph node metastases in bladder carcinoma demonstrated superior detection rates and tumor-to-background ratios (TBR) for FAP imaging." (PMID 40272498, 2025). "Fibroblast-activating protein (FAP), a CAF marker, has been positively connected with lymph node metastasis in clinical samples." (PMID 37927475, 2023). "Fibroblast Activation Protein (FAP), from the EMT pathway, was significantly upregulated in EEC with lymph node metastasis." (PMID 35565317, 2022). "Expression of FAP(+)/BCAT(N) staining combination at the infiltrating front and in lymph node metastasis was also found to be an independent prognostic factor for 5-year FS, together with local invasion (pT)." (PMID 32428869, 2020). "FAP positive specimens more frequently showed lymph node metastases, however, the difference was not statistically significant (21/45, 47% and 2/11, 18%, respectively, p = 0.074; Wilcoxon rank-sum test)." (PMID 37614665, 2023). "Probably due to its cystic morphology, a sole lymph node metastasis with a size of 11 mm showed a negative FAP immunostaining and no tracer uptake in imaging." (PMID 33057927, 2021). "In lymph node metastases of the size between 4 and 6 mm, there was only a weak FAP expression (score 1+) without FAPI uptake." (PMID 33057927, 2021). "Univariate and multivariate analyses were performed to test whether the FAP(+)/BCAT(N) staining combination at the tumor front and in lymph node metastasis was an independent prognostic factor predicting CSS and DFS." (PMID 32428869, 2020).